SH3BP2 (SH3 domain binding protein 2)
Diseases named in the same sentence as SH3BP2 in open-access papers (continued):
Sharing a sentence is not in itself a finding about the gene and the disease.
Lupus- (2 papers, 2019 to 2021). "We have previously reported that SH3BP2 P416R gain-of-function mutation, which results in excessive SH3BP2 protein expression, ameliorates clinical and immunological phenotypes of Faslpr/lpr lupus-prone mice." (PMID 33920631, 2021). "In this study, we investigated the involvement of SH3BP2 in SLE pathophysiology using SH3BP2-deficient mice and Faslpr/lpr lupus-prone mice." (PMID 33920631, 2021). "Collectively, SH3BP2 deficiency improved the lupus-like phenotypes of Faslpr/lpr mice, which is likely caused by SH3BP2-mediated alteration in the myeloid cell differentiation into DCs." (PMID 33920631, 2021). "To this end, we generated conditional B cell-specific SH3BP2-deficient mice and examined if the deletion of SH3BP2 only in B cells improves the lupus-like phenotypes, as observed in the systemic knockout mice." (PMID 33920631, 2021). "Lastly, SH3BP2 deficiency suppressed the differentiation of myeloid cells into DCs in vitro and reduced the number of splenic DCs in the lupus-prone mice." (PMID 33920631, 2021). "Our results demonstrated that Sh3bp2 gain-of-function mutation improved the survival rate and renal involvement in lupus-prone mice via the reduction in anti-dsDNA antibody titer and autoreactive lymphocytes." (PMID 31052273, 2019). "Our results revealed that excess SH3BP2 protein ameliorated immunological and pathological phenotypes in Faslpr lupus-prone mice and that the Sh3bp2 gain-of-function mutation prolonged the survival and reduced the renal involvement in these mice." (PMID 31052273, 2019). "To examine how the Sh3bp2 gain-of-function mutation modulates the immunological phenotypes in Faslpr lupus-prone mice, we determined serum concentrations of the anti-dsDNA antibody (IgG)." (PMID 31052273, 2019). "Sh3bp2 gain-of-function mutation ameliorated clinical and immunological phenotypes in lupus-prone mice." (PMID 31052273, 2019). "Interestingly, SH3BP2 deficiency suppressed the differentiation of dendritic cells in vitro and reduced the number of dendritic cells in the spleen of the lupus-prone mice." (PMID 33920631, 2021). "We hypothesized that SH3BP2 deficiency in B cells suppresses the production of pathogenic antibodies and subsequently ameliorates lupus-like phenotypes in Faslpr/lpr mice." (PMID 33920631, 2021). "Interestingly, our present study has shown that SH3BP2 deficiency also ameliorates the lupus-like phenotypes of Faslpr/lpr mice." (PMID 33920631, 2021). "We noted several distinct features of SH3BP2 deficiency in lupus-prone mice." (PMID 33920631, 2021). "To determine how the Sh3bp2 gain-of-function mutation improves the survival rate of the Faslpr lupus-prone mice, we examined renal involvement, which is a characteristic feature of lupus-prone mice." (PMID 31052273, 2019). "Improved lupus-like phenotypes in SH3BP2-deficient mice led us to consider that the modulation of SH3BP2 expression would be a potential therapeutic approach for SLE." (PMID 33920631, 2021). "We initially assumed that SH3BP2 in B cells would be essential for its regulatory effect on the pathogenesis of lupus because SH3BP2 has been reported to regulate B-cell functions." (PMID 33920631, 2021). "The present study was undertaken to investigate the role of SH3BP2 in a murine systemic lupus erythematosus model." (PMID 33920631, 2021). "As reported in our previous study, increased proapoptotic events mediated by SH3BP2 gain-of-function are considered to ameliorate lupus phenotypes in the Faslpr/lpr lupus model." (PMID 33920631, 2021). "The present study demonstrates that SH3BP2 deletion significantly improves the clinical and immunological phenotypes of lupus-prone Faslpr/lpr mice." (PMID 33920631, 2021). "We thus propose that SH3BP2-mediated alteration of the differentiation into DCs is a possible mechanism for the improvement of lupus-like phenotypes in Sh3bp2Δ/ΔFaslpr/lpr mice." (PMID 33920631, 2021).
Lupus- (continued). "The findings indicate that SH3BP2 in B cells has limited effects on the phenotypes of lupus-prone mice." (PMID 33920631, 2021). "Sh3bp2 gain-of-function (P416R knock-in; Sh3bp2KI/+) mice and lupus-prone B6.MRL-Faslpr mice were crossed to yield double-mutant (Sh3bp2KI/+Faslpr/lpr) mice." (PMID 31052273, 2019). "Our current study indicated that excess SH3BP2 protein suppressed immunological and clinical lupus phenotypes." (PMID 31052273, 2019). "To determine the effect of SH3BP2 on T cells, we examined T cell subsets in lymph nodes from lupus-prone mice and found the ratios of CD4+ T cells, CD8+ T cells, and CD4+CD25+ T cells to be comparable between Faslpr/lpr and Sh3bp2KI/+Faslpr/lpr mice." (PMID 31052273, 2019). "Further analyses using various experimental settings would be required to determine whether SH3BP2-mediated dysregulation of phagocytic activity affects lupus induction and progression." (PMID 31052273, 2019). "Here, we explored the involvement of SH3BP2 in a lupus model." (PMID 31052273, 2019). "Furthermore, we explored the effect of SH3BP2 on splenic DCs of the lupus-prone mice." (PMID 33920631, 2021). "Therefore, increased TNF expression in Sh3bp2 gain-of-function mutant cells might aggravate inflammation in arthritic conditions while alleviating immunological and pathological symptoms in lupus-like conditions." (PMID 31052273, 2019). "In this study, we investigated the involvement of SH3BP2 in SLE pathophysiology, using Sh3bp2 P416R gain-of-function mice and lupus-prone mice carrying the Faslpr mutation." (PMID 31052273, 2019). "Notably, SH3BP2 deficiency in B cells did not rescue the lupus-like phenotypes." (PMID 33920631, 2021). "However, the deletion of SH3BP2 in B cells, unexpectedly, did not retrieve the lupus phenotypes, including aberrant autoantibodies production." (PMID 33920631, 2021).
nephrotic syndrome (2 papers, 2024 to 2025). A collection of symptoms that include severe edema, proteinuria, and hypoalbuminemia; it is indicative of renal dysfunction. "The data also showed variations in the SH3BP2 gene, this gene encodes the SH3BP2 protein which is implicated in nephrotic syndrome." (PMID 40572705, 2025). "To explore the importance of SH3BP2-mediated signaling in nephrotic syndrome, we identified a gain-in-function transgenic Sh3bp2KI/KI mouse that was previously used to study the innate immune system in human cherubism." (PMID 38127456, 2024). "Bioinformatic analysis of human glomerular transcriptome (Nephrotic Syndrome Study Network cohort) revealed upregulated SH3BP2 in MCD and FSGS." (PMID 38127456, 2024). "Immunofluorescence microscopy of Sh2bp2KI/KI mouse kidneys validated the importance of PLCγ2 and VAV2 downstream of SH3BP2 in nephrotic syndrome as suggested by in silico IMPRes analysis of human glomerular transcriptome." (PMID 38127456, 2024). "We surmised that the SH3BP2 signaling complex, given its role across multiple immune cells, may play an important role in immunopathogenesis of nephrotic syndrome." (PMID 38127456, 2024). "We hypothesized that SH3BP2 signaling complex (signalosome) is upregulated in human nephrotic syndrome." (PMID 38127456, 2024). "We used human transcriptomic and clinical data from the Nephrotic Syndrome Study Network (NEPTUNE) to demonstrate that SH3BP2, its partner molecules (especially PLCγ2 and VAV2), and innate immune signaling pathways are upregulated in the glomerular transcriptome in nephrotic syndrome." (PMID 38127456, 2024). "Thus, upregulated SH3BP2, TNF-α, TLR, NLR, and cytokine-cytokine receptor pathway scores and unchanged scores for measles, RLR, and IL-1β pathways in human nephrotic syndrome indicate an important role of SH3BP2-mediated innate immune activation." (PMID 38127456, 2024). "We postulate that SH3BP2 modulates immunopathogenesis of nephrotic syndrome." (PMID 38127456, 2024). "Thus Sh3bp2KI/KI complemented with Sh3bp2–/– mice for in vivo studies and human podocytes for in vitro studies will be valuable to investigate immune dysregulation in nephrotic syndrome." (PMID 38127456, 2024). "Human glomerular transcriptome data suggest that SH3BP2 recruits PLCG2 and VAV2 in downstream signaling in nephrotic syndrome." (PMID 38127456, 2024). "SH3BP2 is expressed in both immune and nonimmune cells, and its upregulation in the tubulointerstitial transcriptome would be anticipated in nephrotic syndrome." (PMID 38127456, 2024).
Noonan syndrome (2 papers, 2013 to 2022). Noonan Syndrome (NS) is characterized by short stature, typical facial dysmorphism and congenital heart defects. "There have been reports of cherubism cases associated with Noonan syndrome without showing mutations at gene SH3BP2, which is considered as an expression of the disease rather than two related entities." (PMID 24382142, 2013). "Since fibrous osseous dysplasia has been described in cherubism and sporadically in Noonan syndrome, sequencing of exon 9 of the SH3BP2 or KRAS, BRAF and PTPN11 genes was performed, but no pathogenic variant was detected." (PMID 33685999, 2022).
osteoporosis (2 papers, 2022 to 2023). A condition of reduced bone mass, with decreased cortical thickness and a decrease in the number and size of the trabeculae of cancellous bone (but normal chemical composition), resulting in increased fracture incidence. "In addition to the roles of 3BP2 in osteoclastogenesis, 3BP2 is also required for osteoblastogenesis since Sh3bp2-/- mice display osteoporosis due to defective osteoblastogenesis." (PMID 36911671, 2023).
periodontitis (2 papers, 2021 to 2022). An acute or chronic inflammatory process that affects the tissues that surround and support the teeth. "In this study, we found that overexpression of DEL-1 downregulated NAMPT and SH3BP2 in gingiva tissues of rats with periodontitis as well as in P. gingivalis-infected THP-1 cells." (PMID 35481344, 2022). "DEL-1 inhibited the expression of NAMPT and SH3BP2 in gingiva tissues of rats with periodontitis as well as in P. gingivalis-infected THP-1 cells." (PMID 35481344, 2022). "In this study, we assessed the role of DEL-1 in P. gingivalis-induced periodontitis, and the effect of DEL-1 overexpression on SH3BP2 expression was examined in vivo and in vitro." (PMID 35481344, 2022). "The in vivo experiments revealed that SH3BP2 expression statistically significantly increased in the gingival tissues of rats with periodontitis, and DEL-1 could inhibit SH3BP2 and NAMPT expression." (PMID 35481344, 2022).
acute myeloid leukemia (1 paper, 2018). Acute myeloid leukemia (AML) is a group of neoplasms arising from precursor cells committed to the myeloid cell-line differentiation. "Finally, both SH3BP2 and MITF may also be useful targets, in other malignancies in which KIT is the driven molecule, such as acute myeloid leukemia (AML), mastocytosis, or certain cases of melanoma." (PMID 29885053, 2018).
bladder urothelial carcinoma (1 paper, 2020). "Until now, the roles of PDGFRA, OLR1, RAC3, PDF, OAS1, and SH3BP2 in bladder urothelial carcinoma remain largely unexplored." (PMID 32733809, 2020).
breast cancer (1 paper, 2025). A primary or metastatic malignant neoplasm involving the breast. "For instance, it showed target pairing between piR-823 and lncRNA for the BRAC1 gene in breast cancer (BC), SH3BP2 in renal cell carcinoma (RCC), and ANKRD28 in hepatocellular carcinoma (HCC)." (PMID 39102033, 2025).
diabetic nephropathy (1 paper, 2024). "Additionally, we compared present results with the effects of diabetic nephropathy on the SH3BP2 signalosome using glomerular transcriptome data (GEO Series accession GSE96804)." (PMID 38127456, 2024). "Additionally, increased SH3BP2 signaling does not appear to be a generalized change across common proteinuric disease conditions as glomerular transcriptome data in diabetic nephropathy (GEO GSE96804) showed unchanged SH3BP2 signalosome score." (PMID 38127456, 2024). "SH3BP2 signalosome score in the glomerular transcriptome was not significantly changed in proteinuric participants (2.53 ± 1.20 g/d) with diabetic nephropathy." (PMID 38127456, 2024).
glomerulosclerosis (1 paper, 2019). A hardening of the kidney glomerulus caused by scarring of the blood vessels. "Sh3bp2 gain-of-function mutation alleviated the poor survival rate, proteinuria, and glomerulosclerosis and significantly reduced serum anti-dsDNA antibody levels in Sh3bp2KI/+Faslpr/lpr mice." (PMID 31052273, 2019).
inflammatory bone diseases (1 paper, 2014). "Further analysis is needed to determine whether activation of SH3BP2-mediated pathways in macrophages and osteoclasts regulates the structural changes of RA and other forms of inflammatory bone diseases." (PMID 25144740, 2014).
lung adenocarcinoma (1 paper, 2025). A carcinoma that arises from the lung and is characterized by the presence of malignant glandular epithelial cells. "In a separate study, the identical SunTag system (dCas9-multiGCN4 + ScFv-TET1CD) was employed to induce the expression of CARD9, SH3BP2, and CNKSR1 in A549 and 1–87 lung adenocarcinoma cell lines." (PMID 40650152, 2025).
mast cell leukemia (1 paper, 2023). Mast cell leukemia is a malignant form of systemic mastocytosis (SM) characterized, most of the time, by the presence of circulating mast cells. "In this study, miR-1246 and miR-5100 were validated by qPCR in the SH3BP2-silenced human mast cell leukemia cell line (HMC-1)." (PMID 36834926, 2023).
rheumatoid arthritis (1 paper, 2014). A chronic, systemic autoimmune disorder characterized by inflammation in the synovial membranes and articular surfaces. "Therefore, modulation of the SH3BP2 expression may have therapeutic potential for the treatment of rheumatoid arthritis." (PMID 25144740, 2014).
Wolf-Hirschhorn syndrome (1 paper, 2012). Wolf-Hirschhorn syndrome (WHS) is a developmental disorder characterized by typical craniofacial features, prenatal and postnatal growth impairment, intellectual disability, severe delayed psychomotor development, seizures, and hypotonia. "Mutations in cherubism that result in a gain-of-function for SH3BP2 is consistent with prior observations that deletions of 4p16.3 in patients with Wolf-Hirschhorn syndrome, which result in loss of one copy of SH3BP2, do not cause a bone resorptive phenotype." (PMID 22640988, 2012).
tumor (6 papers, 2012 to 2023). "Previously, our group reported that silencing of the adaptor molecule SH3 Binding Protein 2 (SH3BP2) downregulated KIT and PDGFRA and microphthalmia-associated transcription factor (MITF) levels and reduced tumor growth." (PMID 36551682, 2022). "Consistent with the results obtained in vitro, a significant delay in tumor growth and tumor volume was observed for the SH3BP2 shRNA cells compared to the NT shRNA control cells." (PMID 29885053, 2018). "Furthermore, SH3BP2 silencing significantly reduces cell migration and tumor growth of imatinib‐sensitive and imatinib‐resistant cells in vivo." (PMID 29885053, 2018). "We next tested the ability of SH3BP2 silencing to prevent GIST tumor growth in a xenograft model." (PMID 29885053, 2018). "Regulation of SH3BP2 transcription is largely unknown but recently evidence emerged that SH3BP2 expression is differentially regulated by hypoxic conditions in tumor cells." (PMID 22640988, 2012). "Finally, we analyzed the ability of SH3BP2 to inhibit tumor growth in vivo." (PMID 29885053, 2018). "Ratio differences of important immune-related AS events (clualt3p199530 NRG1, clualt5p154454 SH3BP2, clualt5p114936 ACKR3, clualt5p152292 IL15, cluir97910 NFKBIB, and clualt5p204621 IKBKG) between tumor and normal tissues are presented." (PMID 37139238, 2023). "In previous work, we showed that silencing of SH3BP2 diminished KIT, PDGFRA, and MITF levels lead to a reduction in tumor growth in vitro and in vivo." (PMID 36551682, 2022). "We previously reported that silencing of SH3BP2 leads to a reduction of KIT expression at both mRNA and protein levels, as well as MITF at the protein level, resulting in a decrease in GIST tumor growth in vitro and in vivo." (PMID 36551682, 2022). "Using this cell line, the deleterious effect of SH3BP2 silencing on tumor formation was more evident than in the GIST882 model, probably due to more efficient SH3BP2 silencing." (PMID 29885053, 2018). "Thus, SH3BP2 silencing decreased oncogenic KIT/PDGFRA levels, reduced MITF levels, led to apoptosis in vitro, and decreased tumor growth in vivo." (PMID 36834926, 2023). "We first performed xenograft experiments with SH3BP2‐silenced GIST882 cells which showed a significant delay in GIST subcutaneous tumor grafting and a reduction in final tumor volume compared to nonsilenced cells." (PMID 29885053, 2018).
SH3BP2 also shares sentences with these, for which no sentence is quoted: genetic disorder (2 papers); apical periodontitis (1); autosomal dominant disease (1); cancer (1); diabetes (1); Evans syndrome (1); hepatocellular carcinoma (1); idiopathic pulmonary fibrosis (1); inflammatory bowel disease (1); liver inflammatory diseases (1); mastocytosis (1); measles (1); melanoma (1); osteoarthritis (1); renal cell carcinoma (1).